MTOR (mechanistic target of rapamycin kinase)
Diseases named in the same sentence as MTOR in open-access papers (continued):
Sharing a sentence is not in itself a finding about the gene and the disease.
infection (continued). "At the same time, SARS-CoV-2-induced reduction of mTOR-dependent glycolysis and protein translation is compatible with the manipulation of the cell cycle or induction of apoptosis, which is used by many viruses as a strategy to promote their infection cycles." (PMID 33182802, 2020). "We demonstrate that lowered mTOR activity in effector CD4+ T cells during the course of Plasmodium yoelii nonlethal (PyNL) infection correlates with the temporal loss of T-bet expression." (PMID 32817333, 2020). "Thus, PI3K/AKT/mTOR signalling and downstream mTOR-sensitive translation are activated in BMDMs early during infection by L. donovani amastigotes or promastigotes." (PMID 32479529, 2020). "Inhibition of the AKT/mTOR pathway in infected macrophages and at early stages of infection in HGECs may exert bacterial clearance effects." (PMID 32230992, 2020). "Here we show that infection with promastigotes or amastigotes of L. donovani leads to an early translational reprogramming in macrophages partially depending on mTOR and eIF4A activity which appears to contribute to both parasite persistence and host cell defense." (PMID 32479529, 2020). "IAV had a significant effect on mTOR transcript levels up to 24 h of infection." (PMID 32326380, 2020). "Although autophagy may be involved in anti-inflammatory responses, autophagy may not play a significant role in LPS-induced inflammation since rafamycin treatment could improve pulmonary injury after LPS infection by down-regulating mTOR." (PMID 32098061, 2020). "mTOR knockdown cell lines were established by lentiviral infection with shmTOR." (PMID 32517736, 2020). "The activation of Akt/mTOR signaling during SARS-CoV-2 infection could be to sustain protein synthesis by increased accession to translation components and by overcoming infection-associated stress by blocking autophagy and apoptosis." (PMID 32691695, 2020). "Furthermore, Foxp3+ cells from aged mice displayed lower levels of mTOR phosphorylation upon infection when compared to young mice (top and bottom)." (PMID 33240286, 2020). "During infection cellular stress responses are activated that normally inhibit mTOR activation, which may act to preserve energy expenditure and prevent cytoplasmic translation of viral proteins." (PMID 32130224, 2020). "Indeed, memory T cells assume a metabolically quiescent state with reduced mTOR signaling during dietary restriction, resulting in increased protection in infection and tumors." (PMID 33170123, 2020). "It is well-known that modulation of mTOR signaling also has major effects on the adaptive immunity such as on the balance between effector versus memory T cells not only in the context of infection, but also autoimmunity and cancer, which is covered by excellent recent reviews." (PMID 31936570, 2020). "Along the same line, blocking mTOR or Akt impaired the production of cytokines after infection." (PMID 32385235, 2020). "This led us to speculate that SARS-CoV-2 can modulate the Akt/mTOR/HIF signaling at various levels to promote its infection." (PMID 32691695, 2020). "A progressive increase in the protein and mRNA levels of mTOR was observed till 24 h of infection, whereas at 48 hpi, a considerable decrease both at the protein and the transcript levels of mTOR was observed, suggesting that the survival of the cell is compromised at later stages." (PMID 32326380, 2020). "Furthermore, c-ABL silencing enhanced nilotinib efficacy in the regulation of autophagy via inhibition of PI3k/Akt/mTOR signaling cascades in BMDM cells after infection with M. bovis." (PMID 31130711, 2019). "BMP4 was shown to effectively inhibit the expression of mTOCR1 signaling members, such as S6k, Deptor, Pras40, Rptor, mTor, and Srebf1 at 36h and/or 72h after Ad-B4 infection, while transiently up-regulating the expression of Lipin1 at 36h after Ad-B4 infection." (PMID 31831718, 2019).
infection (continued). "Having demonstrated that BEFV reduced the phosphorylated form of mTOR in the late stage of infection, we next wanted to confirm whether the downstream targets were also suppressed." (PMID 31601269, 2019). "In mammalian cells, the phosphatidylinositol 3-kinase (PI3K)/Akt/mTOR signaling pathway is the primary pathway that regulates autophagy when cells are exposed to certain conditions, such as starvation, oxidative stress, infection, and tumor suppression." (PMID 31861844, 2019). "Finally, we demonstrate that animals and cells with enhanced ISGylation have increased basal and infection-induced autophagy through the modification of mTOR, WIPI2, AMBRA1, and RAB7." (PMID 31772204, 2019). "Inhibition of mTOR by rapamycin, which can promote the degradation of autolysosomes, can restrain viral RNA synthesis and block viral protein VP1 expression caused by the SDLY107 infection." (PMID 31861844, 2019). "However, in cells transfected with the agonist miRNA cocktail, RV-SA11 infection resulted in downregulation of mTOR and subsequent induction of autophagy marker LC3-II confirming the direct role of these miRNAs in modulating autophagy (lane 5)." (PMID 30718795, 2019). "In addition, mTOR inhibition resulted in increased bacterial proliferation supporting the importance of mTOR-mediated metabolic reprogramming for the control of infection with the intracellular bacterium S. typhimurium." (PMID 31832425, 2019). "Thus, HIF-1α and mTOR are key elements driving the metabolic pathway and immune modulation during the host response to infections." (PMID 30994733, 2019). "However, the addition of rapamycin increased the expression of Mtb-induced TLR-6 expression but inhibited the expression of NF-κB and mTOR in U937 macrophage-like cells of all three conditions of infection." (PMID 30356420, 2018). "Indeed, a pro-autophagic function for miR-155 was shown by its capacity to target multiple players within the mTOR cascade as Rheb, although in response to hypoxia or to infection with avirulent Mtb or BCG vaccine." (PMID 29300789, 2018). "The results suggest that the mTOR pathway is activated during pH1N1 infection." (PMID 30422993, 2018). "Many viruses interfere with or use PI3K-Akt-mTOR pathway to regulate their infection." (PMID 28475412, 2018). "Also, we found that a short period of mTOR inhibition previous to infection induced an inflammatory profile in these macrophages similar to an M1 polarization without iNOS expression." (PMID 29515594, 2018). "Intriguingly, the inhibition of PI3K, Akt, or mTOR activity led to a reduction of intracellular infection in mammary epithelial cancer MCF-7 cells to BCG, indicating a critical role of the PI3K/Akt/mTOR pathway in the immune response of mycobacterial infection." (PMID 30356420, 2018). "Finally, other complementary pathways (e.g. MEK/ERK and MNK/eIF4E phosphorylation) can become activated during prolonged mTOR inhibition or upon infection by viruses." (PMID 30138450, 2018). "On the other hand, various investigators have shown that transplant patients treated with this mTOR inhibitor or got everolimus-based immunosuppressive regimen have better control of pathogen infections or reactivations and, therefore, have better clinical outcomes." (PMID 30619313, 2018). "However, in the later phase of infection, the rapid normalization of cytosolic amino acid levels in Salmonella-infected cells reactivates mTOR at the surface of the SCV and favors bacterial escape from autophagy." (PMID 28783107, 2017). "Inhibition of mTOR, followed by subsequent changes in host cellular activities and hyper-susceptibility of PI3 kinase, akt-1, mTOR, pdi-2, and eef-2 mutants unveiled the role of PI3K/AKT/mTOR pathway, protein folding, and translation machinery in host defense against infection." (PMID 28932706, 2017).
infection (continued). "In conclusion, the results obtained in this study uncover a novel role for HIF-1α in response to H. pylori infection of gastric cells, serving to connect an initial early potentially survival response, downstream of PI3K/mTOR activation, to G1/G0 cell cycle arrest later on following infection." (PMID 28401064, 2017). "By contrast, MAPK1 was upregulated in response to vvIBDV infection, which might indicate inhibition of the Akt/mTOR pathway." (PMID 28086922, 2017). "However, treatment with IFN-γ along with infection distinctly decreased phosphorylation of Thr389 proving mTOR inactivation." (PMID 26757825, 2016). "Subsequently, KEGG pathway analysis of these putative target genes indicated involvement of Wnt signaling pathway, MAPK signaling pathway, TGF-beta signaling pathway, and mTOR signaling pathway, which have been shown to be important during the infection processes of some other viruses." (PMID 27843944, 2016). "Overview of studies demonstrating the role of mTOR in lymphoid cells following pathogen infection." (PMID 27242787, 2016). "During infection with high bacterial burden, autophagy induction might be beneficial, but during a low dose infection with Mtb our data clearly indicate that mTOR inhibition disturbs the controlled growth." (PMID 27302320, 2016). "ANDV infection activates mTOR and increased phosphorylation of S6K1." (PMID 27231932, 2016). "Also, the cells were serum-starved for 10hrs prior to and for the duration of the infections to avoid growth factor-induced MTOR activation." (PMID 27942021, 2016). "Similarly, hyperactivation of AKT and mTOR signaling also occurred in mesenchymal PC-3 cells upon Ad-E1A12 infection." (PMID 27849011, 2016). "DGE and qPCR analysis suggest activation of mTOR would be involved in the infection of CSFV Shimen." (PMID 27330868, 2016). "In addition to lipogenesis, MTOR controls immunity to infection by repressing inflammation and autophagy." (PMID 27942021, 2016). "If Legionella-induced MTOR activity interferes with a host cell death response, it would be predicted that in the presence of TLR-signaling the host Akt/MTOR-ubiquitination pathway will phenocopy the effect of the pharmacological inhibitors in Myd88-/- BMMs infections." (PMID 27942021, 2016). "However, mTOR inhibitors also prevent metabolic remodeling induced by HCMV during infection, thus the effects of the inhibitors are likely pleiotropic." (PMID 27089357, 2016). "Inactivation of the host MTOR-suppression pathway revealed that L. pneumophila sustained MTOR signaling throughout its intracellular infection cycle by a process that required the upstream regulator Phosphatidylinositol-4,5-bisphosphate 3-kinase (PI3K) and one or more Dot/Icm effector proteins." (PMID 27942021, 2016). "Under MTOR suppressing conditions, BMMs with aberrant nuclear morphology infected with ΔflaA bacteria increased gradually starting at 6hrs after bacterial replication is initiated and peaked at 10-14hrs post-infection." (PMID 27942021, 2016). "The results of this study suggest that under infection, a down regulation of translational proteins occurs for both strains, in particular S6 ribosomal protein (part of the mammalian/mechanistic target of rapamycin (mTOR) pathway)." (PMID 27490109, 2016). "Importantly, the expression of MTOR, a master inhibitor of autophagy, was decreased (0.78-fold) following infection with C. concisus BAA-1457." (PMID 27677841, 2016). "The level of phosphorylated ULK1-Ser757 decreased during mid-infection and was only negligibly present at the terminal stage, a pattern that suggested a close relationship of the phosphorylated protein with altered endogenous mTOR." (PMID 26423766, 2015). "Indeed, preventing mTOR-dependent hyper-phosphorylation of eIF4E using MnK or PI3K inhibitors significantly decrease infection efficiency." (PMID 26317997, 2015).
infection (continued). "To explore whether Akt/mTOR signaling is involved in CA16 infection-induced autophagy, we evaluated the phosphorylation of these kinases." (PMID 25853521, 2015). "In addition, it has previously been shown that mTOR is recruited to SCVs in epithelial cells several hours after infection with WT Salmonella, which we confirmed in Hela cells." (PMID 24901456, 2014). "However the basal level of expression of the proteins like Akt, GSK3β, Ras, mTOR, 4EBP1 and S6K remain unchanged during infection as well as in presence of GA." (PMID 24959709, 2014). "Having shown that mTOR activation plays an essential role in triggering the Warburg-like effect during WSSV infection, we next explored what happens to WSSV viral gene expression and viral DNA genome replication when the Warburg-like effect is suppressed by inhibition of the mTOR pathway." (PMID 24945378, 2014). "When the expression of phospho-mTOR was monitored by Western blot assay we observed an increased expression between 12 and 24 hpi, showing that infection with the RHDV stimulates the mTOR signalling pathway in parallel to the development of the autophagic process." (PMID 24490870, 2014). "In addition, changes to a large subset of the protein intermediates of the insulin/mTOR pathway in the skeletal muscle were altered by infection." (PMID 23682635, 2013). "However, the inhibition of mTOR activity during the late stage of infection is due to the effects of the SV40 small T antigen." (PMID 24098109, 2013). "Since the bacteria used in our studies were grown in MHB, we sought to verify that infection of cells with F. tularensis grown in BHI compared to those grown in MHB resulted in a similar phosphorylation pattern of mTOR downstream effector molecules, and a similar ability to invade macrophages." (PMID 24312679, 2013). "mTOR activity is induced early in infection but inhibited as infection progresses." (PMID 24098109, 2013). "Therefore, we envision a targeting regime that involves the simultaneous inhibition of 4E-BP1 in APCs and the activation of mTOR in CD4 T cells to enhance the host protective Th1 response in the early stages of infection." (PMID 23028309, 2012). "Also, treatment of LCMV infected mice post-infection with rapamycin, an mTOR inhibitor, surprisingly increased the quantity and quality of LCMV specific CD8+ T cells." (PMID 22558103, 2012). "We focused on 8 inhibitors targeting mTOR and/or PI3Ks selected from various stages of pre-clinical and clinical development, and tested them against in vitro parasite cultures and in vivo models of infection." (PMID 21886855, 2011). "Furthermore, this review systematically integrates the dual role of the PI3K/Akt-mTOR pathway in infection immunity, aiming to elucidate its central position as a core for host defense and pathogen evasion, and to provide a clear theoretical framework for subsequent targeted therapeutic research." (PMID 41982459, 2026). "Compelling evidence from the literature establishes that infection of epithelial cells with intracellular bacterial pathogens such as S. flexneri and L. monocytogenes induces a state of amino acid starvation, as determined by the early delocalization of mTOR from lysosomes." (PMID 40853005, 2025). "However, SFV and CHIKV have also been shown to activate PI3K-Akt-mTOR activity early in infection, which may lead to an inhibition of autophagy." (PMID 40042894, 2025). "After infection, the body provides energy to cells in the way of autophagy to promote the development, differentiation and maturation of immune cells, and promotes the recognition and presentation of antigens in combination with mTOR signaling pathway to initiate and regulate innate immunity." (PMID 40375996, 2025).
infection (continued). "However, there were 4 patients that required an adjustment of tacrolimus dose related to clinical reasons; to reduce the tacrolimus trough levels (considered too high), an infection episode (overimmunosuppression), and incorporating the mTOR inhibitor instead of MMF." (PMID 41155603, 2025). "Although mTOR inhibitors like rapamycin and RAD001 show considerable promise in reversing immune aging, they may cause side effects such as impaired wound healing, increased susceptibility to infections, and metabolic disturbances." (PMID 41299782, 2025). "Together, these findings highlight the complexity and dynamic nature of mTOR signaling, which combines pro-inflammatory and homeostasis restoration properties, and underscore its potential as a therapeutic target for addressing short and long-lasting effects of infection." (PMID 40177636, 2025). "Accumulating evidence showed that some pathogens could alter immune responses or cell metabolisms through activating mTOR signaling pathway to facilitate their survival and blocking mTOR signaling exerted strong protective effects against infections induced by bacteria, virus, and parasite." (PMID 39114448, 2024). "During infection, pathogens may target mTOR to hijack or disturb host immune processes." (PMID 38515037, 2024). "Our data demonstrate that mTOR inhibition increases the production of pro-inflammatory cytokines in rickettsia-infected cells, suggesting that mTOR may also contribute to the balance of pro-versus anti-inflammatory mediators during infection." (PMID 38399700, 2024). "Such preventative measures include HLA-matched transplantation, avoidance of endothelial toxins (such as mTOR inhibitors), use of conditioning regimens with a reduced intensity that may minimize endothelial injury and, most importantly, vigorous infection control." (PMID 36674666, 2023). "After HIRRV infection under 10 °C and 20 °C, the enriched immune-related DEPs were both associated in RLR and NLR signaling pathways, apoptosis, phagosome and lysosome, and the DEPPs were also both involved in spliceosome, mTOR signaling pathway and RNA transport." (PMID 37627029, 2023). "Mm-ESAT-6M83I and Mm-ESAT-6M93T infections did not kill macrophages in mTOR-deficient zebrafish." (PMID 36103894, 2022). "In addition, 12 and 8 hits in mTOR inhibit AdV3 and AdV5 infection in Vero cells, respectively." (PMID 35632701, 2022). "Thus, it is possible that Mtb-mediated mTOR/Akt signaling may play a major role for suppression of macroautophagy during infection." (PMID 33828998, 2021). "However, after 4 h of infection, p-mTOR signal could be detected in the ctpFCKD, suggesting the gradual restoration of p-mTOR levels." (PMID 33042857, 2020). "We identified that infection with murine cytomegalovirus does not trigger an earlier onset of the disease but instead exacerbates the complex IV deficiency and causes alterations in mTOR signalling, energy metabolism and neuromuscular morphology." (PMID 32130224, 2020). "However, some of these effects could be blocked by the addition of rapamycin indicating that mTOR mediated mechanisms play a central role in regulation of TCA enzymes in the course of infection which may be, however, also affected by the pathogen." (PMID 31832425, 2019). "Moreover, replication complexes are efficiently internalized from the cell periphery for SFV but not CHIKV, and this reduction in CHIKV replication complex internalization correlates with a reduced stimulation of the prosurvival PI3K-Akt-mTOR pathway in comparison to that in SFV infection." (PMID 29875241, 2018). "Thus, the dauer formation along with intestinal atrophy in infected nematodes suggested that might be due to the downregulation of mTOR during infection." (PMID 28932706, 2017).